ENSG00000293268 (endogenous retrovirus group K member 5)
Synonyms: LOC124906262
Gene: Protein-coding gene on chromosome 3 (101,686,827 to 101,713,301, forward strand). Ensembl gene ENSG00000293268.
Gene Ontology:
Molecular function: nucleic acid binding; structural molecule activity; zinc ion binding
Biological process: viral process
Cellular component: plasma membrane
Homologues: Orthologues: rat LOC134485158 (21% identical), rat Adal (20% identical).